SHH (sonic hedgehog signaling molecule)
Diseases named in the same sentence as SHH in open-access papers (continued):
Sharing a sentence is not in itself a finding about the gene and the disease.
colorectal cancer (18 papers, 2010 to 2025). A primary or metastatic malignant neoplasm that affects the colon or rectum. "Taken together, these results suggest that the SHH signaling pathway plays a major role in inhibition of colorectal cancer stemness by 1′-O-methyl-averantin." (PMID 36797277, 2023). "ID1 promoted the stemness phenotype through the activation of the WNT/SHH signaling pathway in brain and colorectal cancer." (PMID 37759448, 2023). "Our findings reveal a new mechanism by which ALKAL1 participates in colorectal cancer migration and invasion via activating the SHH signaling pathway." (PMID 33391411, 2021). "Taken together, our results uncover a novel mechanism of ALKAL1 contributing to the activation of SHH signaling pathway in colorectal cancer progression." (PMID 33391411, 2021). "ALKAL1 silencing inhibited tumorigenesis, metastasis and invasion of colorectal cancer cells, and inhibited SHH signaling pathway, which is essential for ALKAL1 induced migration." (PMID 33391411, 2021). "In summary, our findings reveal that ALKAL1 plays an important role in colorectal cancer migration and invasion via activating SHH signaling pathway." (PMID 33391411, 2021). "Previous studies have demonstrated that the SHH signaling pathway also plays an important role in proliferation, angiogenesis, stemness, and metastasis in various cancers including colorectal cancer." (PMID 33391411, 2021). "To confirm the effect SHH inhibitors on the SHH signaling pathway in colorectal cancer, we investigated their effects on proliferation and SHH/Patched/Smo/Gli signaling in HT-29 colorectal cancer cells." (PMID 26716648, 2016). "For example, in colorectal cancer, overexpression of Gli1 (a downstream component of the SHH signaling pathway) inhibits Wnt signaling and colorectal cancer cell proliferation, even in cells possessing the stabilizing mutation of β-catenin." (PMID 25713298, 2015). "A colorectal cancer study demonstrated that SHH, Gli1, and FOXM1 mRNA expression levels were higher in colorectal adenocarcinomas than in adjacent normal colon tissue." (PMID 24325450, 2013). "In addition, we conducted independent IHC experiments for three genes—EPOP, WDR72, and SHH—which have rarely been validated by immunohistochemistry in previous studies of colorectal cancer." (PMID 41425595, 2025). "Collectively, the data show that 1′-O-methyl-averantin suppresses colorectal cancer stemness by regulating the SHH and Notch signaling pathways, suggesting that it may have potential as a therapeutic drug." (PMID 36797277, 2023). "We further examined the role of ALKAL1 in SHH signaling pathway in colorectal cancer cells." (PMID 33391411, 2021). "Furthermore, ALKAL1 silencing inhibits migration and invasion, and SHH signaling pathway of colorectal cancer cells." (PMID 33391411, 2021). "The ethanol extract of S. barbata could inhibit tumor angiogenesis in a colorectal cancer mouse xenograft model by suppressing the SHH pathway." (PMID 23815868, 2013). "In conclusion, here for the first time we demonstrate that Scutellaria barbata D. Don inhibits colorectal cancer growth in vivo via inhibition of SHH-mediated tumor angiogenesis, which may in part explain its anti-cancer activity." (PMID 22949805, 2012). "It has been reported that SHH signaling can maintain SOX9 overexpression in skin tumors and colorectal cancer." (PMID 26588701, 2015). "The researchers also found strong correlations between expression of SHH and FOXM1 and between expression of Gli and FOXM1 in colorectal cancer cells." (PMID 24325450, 2013). "However, the specific mechanism responsible for the improved outcomes in colorectal cancer patients with high ALKAL1 expression, the biological role of ALKAL1 overexpressing in colorectal cancer cell lines and the targets of ALKAL1 in SHH signaling pathway were not mentioned in this manuscript." (PMID 33391411, 2021).
hepatocellular carcinoma (17 papers, 2013 to 2025). A malignant tumor that arises from hepatocytes. "In the present study we identified the role of Sonic Hedgehog (SHH) pathway in fatty changes associated with DEN + CCl4 induced hepatocellular carcinoma model at different stages and substantiated the findings with clinical-samples." (PMID 32577158, 2020). "Hypoxia, a common feature of many solid tumors, including hepatocellular carcinoma (HCC), has been associated with resistance to chemotherapy in part through the activation of the Sonic Hedgehog (SHh) pathway." (PMID 31616295, 2019). "Overexpression of SASH1 in hepatocellular carcinoma cells was found to inhibit SHH, SMO, PTC, and GLI1 expression, thereby reducing proliferation, migration/invasion, and EMT progression." (PMID 38498906, 2024). "Tian suggests that the SHH signaling pathway contributes to the invasiveness of hepatoma cells, while Fan’s findings indicate that abnormal SHH signaling has an impact on the invasiveness of HCC cells." (PMID 38730691, 2024). "Increased levels of signaling pathway components (SMO, SHH, Gli1, Gli2) have been observed in hepatocellular carcinoma cells in culture and in cells from tumors excised from patients." (PMID 38927059, 2024). "Ligand-dependent activation involves ligand overexpression—SHH protein overexpression promotes adenoma progression to hepatocellular carcinoma." (PMID 38927059, 2024). "Mechanistically, a previous study demonstrated that BRD4 regulated MMP-9 expression through the SHH signaling pathway in hepatocellular carcinoma cells." (PMID 34421353, 2021). "We also checked the expression of SHH and lipogenic molecules in hepatocellular carcinoma patients’ FNAC (Fine Needle Aspiration Cytology) samples." (PMID 32577158, 2020). "Sonic Hedgehog (SHH) pathway is activated in hepatocellular carcinoma but its role in regulation of lipogenic molecules during the hepatocarcinogenesis is not known." (PMID 32577158, 2020). "Our results corroborated these findings in hepatocellular carcinoma model and notably, we also found a strong positive correlation between the SHH expression and the expression of E2F1, FASN, and SREBP1c." (PMID 32577158, 2020). "Although, the SHH pathway is activated in hepatocellular carcinoma but its role in regulating lipogenesis during the process of hepatocarcinogenesis is not documented." (PMID 32577158, 2020). "To explore the role of SHH in lipogenesis and adipogenesis we inhibited SHH pathway in a hepatocellular carcinoma cell-line Hep3B." (PMID 32577158, 2020). "SHH/SMO signaling pathway activates in cancer stem cells (CD133+) of the mouse hepatoma cell line Hepa1-6." (PMID 32962123, 2020). "Our study presents atypical niche for SHH pathway through its control over lipogenesis in hepatocellular carcinoma animal and cell model." (PMID 32577158, 2020). "Neoplasms with activated SHH signaling pathway in cancer stem cells consist of glioblastoma, chronic myeloid leukemia, multiple myeloma, hepatocellular carcinoma and cancers of the colon, breast and pancreas." (PMID 32962123, 2020). "They conducted a co-culture experiment with human hepatoma cells (HCC-LM3), bufalin, and SHH signaling pathway inhibitors (GANT61, cyclopamine) for 72 h." (PMID 38730691, 2024). "The expression levels of SHH, E2F1, and lipogenic molecules were checked at different stages of hepatocellular carcinoma." (PMID 32577158, 2020). "For example, in hepatocellular carcinoma HCC cells, ROS-induced NRF2 activation upregulated the expression of sonic hedgehog homolog (SHH), ultimately activating sonic hedgehog pathway." (PMID 33968932, 2021).
ovarian carcinoma (17 papers, 2009 to 2025). A malignant neoplasm originating from the surface ovarian epithelium. "Ovarian CAFs also induce angiogenesis by secreting VEGF-C via induction by Sonic Hedgehog (SHH) from ovarian cancer cells." (PMID 36672620, 2023). "SHH signaling promotes epithelial-mesenchymal transition by targeting PI3K/AKT signaling in ovarian cancer." (PMID 37815888, 2023). "Our findings provide a theoretical basis for simultaneously inhibiting the SHH pathway and autophagy in the treatment of ovarian cancer." (PMID 34076346, 2021). "Our findings provided the experimental basis for simultaneously inhibiting the SHH pathway and autophagy as a new effective therapeutic strategy for patients with ovarian cancer." (PMID 34076346, 2021). "All these results indicate that inhibition of the SHH pathway induced autophagy through the PI3K/AKT dependent pathway in ovarian cancer cells." (PMID 34076346, 2021). "Inhibition of SHH signaling by cyclopamine (Cyp) enhanced the autophagy and promoted autophagic flux in ovarian cancer cell lines through PI3K/AKT signaling pathway." (PMID 34076346, 2021). "All data suggest that autophagy contributes to ovarian cancer migration induced by inhibition of the SHH pathway." (PMID 34076346, 2021). "For ovarian cancer, inhibiting the SHH signaling pathway by cyclopamine (Cyp), an inhibitor of the SHH pathway, resulted in the reduction of ovarian cancer cell viability, as well as arresting the tumor growth in vivo." (PMID 34076346, 2021). "In this study, we discussed the activation of the SHH pathway and autophagy in ovarian cancer and further examined the influence of the SHH signaling pathway on autophagy." (PMID 34076346, 2021). "Collectively, all data suggest that inhibition of the SHH signaling pathway by Cyp can activate autophagy in ovarian cancer cells." (PMID 34076346, 2021). "In the present study, we found that inhibition of the SHH pathway induced autophagy in ovarian cancer cells." (PMID 34076346, 2021). "Of note, Sonic Hedgehog (SHH) secreted from ovarian cancer cells activates Hh signaling in CAFs, inducing VEGF-C expression and promoting lymphangiogenesis in vitro and in vivo." (PMID 31888563, 2019). "Ovarian cancer CAFs have also been shown to induce angiogenesis by secreting VEGF-C as a result of induction by Sonic Hedgehog (SHH) from ovarian cancer cells." (PMID 30380628, 2018). "We determined here that Sonic Hedgehog (SHH) secreted by ovarian cancer (OC) cells activated Hh signalling in CAFs and promoted the proliferation of CAFs." (PMID 28978035, 2017). "To assess their potential prognostic value, we analyzed the correlation between the expression levels of the following eight components of the Hedgehog signaling pathway on the progression-free (PFS) and overall survival (OS) in ovarian cancer: SHH, GLI1, GLI2, GLI3, PTCH1, PTCH2, HHAT, and SUFU." (PMID 40565349, 2025). "Using the database Kaplan–Meier plotter, which includes the gene expression and survival data of 1565 ovarian cancer patients, higher expression levels of the genes SHH, PTCH1, PTCH2, and GLI1 displayed better survival correlations, while GLI, GLI3, and SUFU correlated with adverse outcomes." (PMID 40565349, 2025). "This highlights that inhibition of the SHH pathway may serve as a target for the treatment of ovarian cancer." (PMID 34076346, 2021). "Since the activity of the SHH pathway is notably related to autophagy activity, we sought to detect whether autophagy was upregulated in ovarian cancer after Cyp treatment." (PMID 34076346, 2021). "Furthermore, high expression of FoxR2 in ovarian cancer stimulates angiogenesis and activates the SHH pathway, which affects the malignant behavior of this cancer." (PMID 34439332, 2021). "Interestingly, a previous study revealed that downregulation of the SHH pathway with GANT‐61 has proved to be more effective than Cyp in the context of ovarian cancer." (PMID 34076346, 2021).
ovarian carcinoma (continued). "In addition, we also observed a negative correlation between SPOP and SUFU accompanied by dysregulated SHH signaling in ovarian cancer." (PMID 34021128, 2021). "Our findings suggest that inhibition of the SHH pathway and autophagy may be a potential and effective therapy for the treatment of ovarian cancer." (PMID 34076346, 2021). "The Sonic Hedgehog (SHH) signaling pathway is vital for embryonic development and tissue homeostasis, and aberrant activation of this pathway is closely related to tumorigenesis and progression of many types of human cancer including ovarian cancer." (PMID 34076346, 2021). "All these data suggest that inhibition of the SHH pathway may be an effective treatment strategy in ovarian cancer." (PMID 34076346, 2021). "Our findings suggest that targeting the SHH pathway and autophagy may be a potential therapeutic strategy for ovarian cancer patients." (PMID 34076346, 2021). "Furthermore, inhibition of the SHH pathway promoted migration of ovarian cancer cells in vitro through induction of autophagy." (PMID 34076346, 2021). "In this manuscript, we show that SHH signaling was active in ovarian cancer tissues." (PMID 34076346, 2021). "Expression of SHH was found in 11 of 34 (~32%) ovarian cancers." (PMID 19943941, 2009). "Hence, the authors suggested that SHH signaling may be a target for inhibition of ovarian cancer progression." (PMID 34439332, 2021). "The Sonic Hedgehog (SHH) signaling pathway plays an important role in various types of human cancers including ovarian cancer; however, its function and underlying mechanism in ovarian cancer are still not entirely understood." (PMID 34076346, 2021). "Indeed, endogenous Six1 regulates SHH expression in A2780 ovarian cancer cells." (PMID 28604738, 2017). "SHH, HHAT, PTCH1, and PTCH2 overexpression further improved the survival rates of ovarian cancer patients, particularly when optimal debulking was possible." (PMID 40565349, 2025). "We analyzed the mRNA expression profiles of HH-related genes—SHH, HHAT, PTCH1, GLI1, GLI2, GLI3, and SUFU—in two ovarian cancer cell lines." (PMID 40565349, 2025). "We detected the expressions of SHH and SQSTM1 in borderline ovarian tumor tissues, epithelial ovarian cancer (EOC) tissues and benign ovarian tumor tissues." (PMID 34076346, 2021). "However, the interaction between the SHH pathway and autophagy in ovarian cancer remains unclear." (PMID 34076346, 2021). "In our study, the significant upregulation of SHH and SQSTM1 was observed in borderline and EOC, suggesting the activation of SHH signaling and inhibition of autophagy in ovarian cancer." (PMID 34076346, 2021). "SHH and SQSTM1 were found to be highly expressed in the samples of borderline ovarian tumors, and even higher in epithelial ovarian cancer (EOC), compared with those of benign ovarian tumors." (PMID 34076346, 2021). "To investigate this possibility, we treated ovarian cancer cells with recombinant BMP4 and analyzed SHH expression via qRT-PCR." (PMID 26755648, 2016). "We found up‐regulation of SHH and accumulation of SQSTM1/P62 in epithelial ovarian cancer." (PMID 34076346, 2021). "To determine how galectin-3 could regulate the stemness phenotype of ovarian cancer cells, we measured the mRNA expression of Notch, WNT/β-catenin, and SHH signaling pathway related genes in galectin-3-depleted SKOV3 cells." (PMID 27626163, 2016). "In addition to SHH, we also detected expression of SMO and Su(Fu) in 17 ovarian cancers." (PMID 19943941, 2009). "Therefore, we hypothesized that inhibition of the SHH signaling pathway may affect the progression of ovarian cancer through the regulation of autophagy, which has not been investigated previously." (PMID 34076346, 2021). "In the COV318 ovarian cancer cell line, BMP4 treatment induced IHH rather than SHH." (PMID 26755648, 2016).
colon carcinoma (16 papers, 2010 to 2025). "Likewise, SHH signalling dysregulation has been reported to contribute to metastasis and angiogenesis in colon cancer, and termination of SHH signalling through glioma-associated oncogene (GLI1) inhibition resulted in the inhibition of proliferation in colon cancer." (PMID 36701089, 2023). "The same is true for colon cancer cells, where SHH and GLI1 expression are increased after irradiation and contribute to tumor repopulation after radiotherapy." (PMID 38731849, 2024). "BBR inhibits colorectal tumor development A previous study showed that BBR reduces paracrine sonic hedgehog (SHH) signaling, which in turn reduces colon cancer growth in vitro and in vivo." (PMID 36937842, 2023). "To confirm the involvement of the SHH and Notch signaling pathways in physciosporin-induced reduction of colon cancer cells, we subjected CSC221 cells overexpressing Gli1/2 and/or ΔEN1 to spheroid assays with exposure to physciosporin for 14 days." (PMID 31795147, 2019). "Preclinical and clinical trials are also underway to test the efficacy of SHH inhibitors in repression of angiogenesis of breast and colon tumors via potentially targeting the VEGF activation." (PMID 28507311, 2017). "Experimental evidences have shown that over expression of SHH and IHH can cause up regulation of GLI proteins, or over activation of cytoplasmic protein RAS can also up regulate GLI proteins in Hedgehog pathway and are responsible for Colon cancer." (PMID 23935937, 2013). "Thus, using qRT-PCR, the expression of GLI1, PTCH1, GLI2 and SHH was determined in all human colon carcinomas examined." (PMID 20957031, 2010). "The aberrant state of the SHH signaling pathway may be involved in the development of colon cancer." (PMID 29670664, 2018). "We found that in our simulation result of Colon cancer model, hedgehog ligands IHH and SHH, RAS in cytoplasm were also activating the GLI transcription factors." (PMID 23935937, 2013). "Similarly, five genes including TOP2A, REL, SHH, ROS1, and CHEK2 in colon cancer gene network and three genes including RBL1, MAPK9, and PIK3CA in adenocarcinoma of lung gene network are selected." (PMID 29670664, 2018). "Compared to the colon cancer cell xenograft model, colospheres induced significant faster tumorigenesis and larger tumors (data not shown), whereas SHH inhibitors significantly inhibited tumorigenesis." (PMID 26716648, 2016). "In the intestinal epithelial cells IEC-6 and colon cancer cells HCT-116, IL-6 expression and its signaling were assessed with SHH inhibitors and levels of other inflammatory mediators, proliferation, apoptosis, tumorsphere formation, and tumorigenesis were also measured." (PMID 26716648, 2016).